CTLA4 (cytotoxic T-lymphocyte associated protein 4)
Diseases named in the same sentence as CTLA4 in open-access papers (continued):
Sharing a sentence is not in itself a finding about the gene and the disease.
tumor (continued). "In murine HCC models, immune checkpoint inhibitors led to an increase in IDO expression by HCC tumor cells via an IFN-γ-dependent mechanism, and this promoted resistance to single-agent CTLA-4 inhibition and was overcome with IDO inhibitor 1-methyl-D-tryptophan." (PMID 38038862, 2024). "This study employs a computational biology tool (in silico approach) to craft aptamers capable of binding to dual receptors, namely, inhibitory CTLA4 and NKG2A, thereby unleashing both T and NK cells and enhancing CD8+ T and NK cell functions for tumor cell lysis." (PMID 38473398, 2024). "In this study, the expression of FAM110B was positively correlated with various immune checkpoints such as PDCD1, CTLA4, EDNRB, TLR4, etc., indicating that FAM110B may be a new target for tumor immunotherapy." (PMID 39170745, 2024). "We were surprised and disappointed that RT + anti-GD2 immunocytokine (IC) + anti-CTLA-4 did not slow the progressive growth of this tumor any more than the minimal slowing seen with 12 Gy RT alone." (PMID 38731089, 2024). "The combinatorial blockade of PD-1 and CTLA-4 failed to control tumor growth in the group treated with clodronate liposome." (PMID 38517331, 2024). "Consistently, ICA supplemented mice exhibited increased abscopal tumor growth after RIT with anti-CTLA4 compared to RIT treated mice without ICA." (PMID 38500667, 2024). "A study supported the idea that combining cordycepin with CTLA-4 blockade could modify the effector and exhaustion status of CD8+ T cell, thereby bolstering CD8+ T cell-mediated anti-tumor immunity in the TME." (PMID 39660124, 2024). "Similarly, in KIRP SIGLEC12 positive tumours, a weak positive correlation in PDCD1 (Fig. 4C1), CD274 (Fig. 6C2), CTLA4 (Fig. 6C3), IL-2 (Fig. 6C4) was observed." (PMID 38268823, 2024). "Dorsal MLV ablation reduced the efficacy of anti-PD-1/ CTLA-4 combination therapy for GL261 tumors, while mice with tumors overexpressing VEGF-C consistently showed decreased tumor sizes and tumor weight, highlighting the critical role MLVs play in anti-tumor therapy." (PMID 38808718, 2024). "Analyses of Tregs in the HBV-associated HCC tumor microenvironment showed a more immunosuppressive and effective status, with increased expression levels of FOXP3, PD-1, CTLA-4, ICOS, and LAG-3 compared with non-HBV HCC." (PMID 38793588, 2024). "In CRC, increased regulatory T cells (Tregs) in the tumor microenvironment may upregulate CTLA-4, which dampens immune responses through high CTLA-4 expression." (PMID 38415252, 2024). "Ligation of adenosine receptors (A2aR and A2bR) on the surface of anti-tumor T cells subsequently triggers the upregulation of PD1 and CTLA4 on the T cell surface, resulting in the inhibition of IFN secretion and collectively culminating in the functional suppression of the anti-tumoral response." (PMID 39650654, 2024). "Tumours with low glucometabolic levels may benefit from anti-CTLA-4 therapy; hence, a combination of anti-CTLA-4 and anti-PD1/PD-L1 therapies may have a synergistic effect in the treatment of advanced malignancies." (PMID 39286684, 2024). "Although uptake of 18F-FLT at tumor sites did not correlate with response to anti-CTLA-4 therapy, they did show a correlation between increased spleen uptake and overall increased response to therapy." (PMID 39104861, 2024). "Remarkably, the vesiculation of the CTLA-4 inhibitor in PEGylated liposomes led to a 5-day increase in the median survival time (MST), a tumor growth delay (TGD) of 11.8%, a higher effector T cells (Teff) to regulatory T cells (Treg) ratio and a greater CD8 + T cells number." (PMID 37587290, 2024). "While TDO overexpression in tumor cells can promote tumor growth through suppression of the anti-tumor immune response, inhibition of TDO can restore tumor suppression and enhance the efficacy of CTLA-4 blockade therapy." (PMID 39211039, 2024).
tumor (continued). "In our study, we found that high PSMB2 expression may induce the upregulation of CD274, CTLA4, HAVCR2, LAG3, PDCD1, PDCD1LG2 and SIGLEC15, which are molecules on immune cells that facilitate tumor immune escape." (PMID 38467767, 2024). "Conversely, HLA class II expression on tumor cells proved to be predictive of anti-PD-1 efficacy but not anti-CTLA-4 effects." (PMID 39766316, 2024). "Considering the distinct tumour immune microenvironment in groups with low and high GLYAT expression, we conducted IPS analysis to assess the potential responsiveness to immunotherapy targeting PD‐1 and CTLA‐4." (PMID 39495775, 2024). "Over the last decade, several monoclonal antibodies targeting immune checkpoint molecules, such as PD-1 and CTLA-4, have been developed and granted FDA approval for the treatment of various solid tumors by reversing T cell dysfunction, leading to tumor killing." (PMID 39273502, 2024). "The use of immune-checkpoint inhibitory antibodies targeting these receptors or their ligands has recently revolutionized the treatment of several tumor entities, but only a modest antitumor activity was observed in patients suffering from DLBCL on PD-1 and CTLA-4 blockade therapy." (PMID 38340727, 2024). "Blocking CTLA-4 inhibits Tregs, reactivates T cells suppressed within the TME, and accompanies an increase in IFN-γ production, thereby inducing PD-L1 expression in the TME and subsequently inhibiting T cell anti-tumor responses." (PMID 38762484, 2024). "Therefore, the high expression of CTLA-4 in TME will inhibit proliferation and activation of T cells through multiple mechanisms, inducing tumor immune escape." (PMID 39635535, 2024). "Of note, a PD-L1/CD80 cis-heterodimerization has been reported on APCs, able to preserve the CD80 capacity to activate CD28, thereby supporting the sustained functionality of intra-tumor CD28+ T cells while repressing the inhibitory activity of PD-1 and CTLA-4." (PMID 39684559, 2024). "Importantly, the T‐cell exhaustion biomarkers (LAYN, CTLA4, and HAVCR2) were highly expressed in the tumor tissues." (PMID 38204220, 2024). "Additionally, another one cluster in tumor region the was characterized by lymphocytes and immune inhibitory markers (including CD4, CD8, NK, NKT, B cells, memory T, LAG3, TIM3, CTLA4, IDO and PD-1)." (PMID 38373959, 2024). "In cancer, Blimp-1 regulates the negative costimulatory molecules (CTLA-4, PD-1, Tim-3, and Tigit) to promote T cell exhaustion and aid tumor cells in evading the immune system." (PMID 39171524, 2024). "Anti–CTLA-4 antibody along with anti–PD-1 therapy failed to control tumor growth and extend survival of mice." (PMID 39485838, 2024). "The interaction of CTLA-4 and B7 (CD80 or CD86) inhibits signal transmission to T cells, which plays a key role in maintaining homeostasis of immune responses as well as in inducing immune escape of tumor cells." (PMID 39354625, 2024). "Western blot analyses were performed for all the groups except for APG157 + anti‐CTLA‐4 groups because there was no tumor available for this analysis." (PMID 38686626, 2024). "In addition, we found a higher proportion of FGFBP2+ NK cells, CTLA4+ T cells, and a lower proportion of LAG3+ T cells in tumor tissues compared to normal tissues." (PMID 38604154, 2024). "Anti-PDL1 + 16 Gy provided no additional benefit relative to IgG + 16 Gy, whereas anti-CTLA4 + 16 Gy achieved a notable tumor growth delay and fully cured one-third of the mice." (PMID 39199612, 2024). "If the task of tumor eradicating has not been completed whereas the expression of CTLA-4 is triggered, the T cells will be inactivated and unable to complete this complex task." (PMID 38257366, 2024). "Furthermore, EVs from tumor cells of patients with cachexia and hepatocellular carcinoma carrying CTLA-4 have been shown to promote tumor cell proliferation and metastasis through the PTEN/CD44 pathway within the tumor microenvironment." (PMID 39528800, 2024).
tumor (continued). "For example, in Checkmate 227 study, nivolumab (anti-PD-1) plus ipilimumab (anti-CTLA-4) achieved durable clinical benefit in all patients regardless of tumor PD-L1 expression." (PMID 38280003, 2024). "Indeed, PD-1 modulates effector T-cell activity in peripheral tissues and in the tumour microenvironment (TME), whereas CTLA-4 prevents T-cell activation." (PMID 38610929, 2024). "Thus, within the tumor, the CD80 is more likely to engage CTLA4 than CD28, thereby dampening the function of T cells at attacking the tumor." (PMID 39575257, 2024). "CTLA-4 and LAG-3 were induced in all patients after tumor interaction." (PMID 39475596, 2024). "Monoclonal antibodies (mAbs) targeting CTLA-4 have revolutionized cancer treatment by inducing lasting tumor regression, although their mechanisms of action are not fully understood." (PMID 39290699, 2024). "High MAEL expression was associated with few CD8+ T cells in tumor center (P=0.040), tumor margin (P=0.016), and total area (P=0.026), high TMB (P=0.013), and low expression of PDCD1 (P=0.003) and CTLA4 (P=0.049) rather than CD274 (P=0.12)." (PMID 38301040, 2024). "To evaluate the effects of CTLA-4 blockade in our lymphocyte-depleted TC-1 tumor model, we treated tumors with RT and either vehicle or a blocking antibody against CTLA-4 that does not deplete Tregs on successive days." (PMID 38349740, 2024). "CTLA4 plays a role in inhibitory receptors (checkpoints) that limit autoreactivity and T cell overactivation, also known as noninflamed tumor or cold tumor." (PMID 39499374, 2024). "Y1.7LI-rechallenged mice that rejected Y1.7LI tumors upon neo VAX or anti-CTLA-4 and/or anti-PD-1 initiated on day 7, but not untreated naïve mice, showed no detectable tumor upon secondary challenge." (PMID 38187708, 2024). "However, the clinical benefit of adding anti-CTLA-4 to anti-PD-1/PD-L1 therapy appears greatest in TMB-high tumors, which have increased tumor immunogenicity resulting from high expression of tumor neoantigens." (PMID 38430375, 2024). "As CTLA-4 blockade significantly reduces Treg infiltration, the he combined administration of VISTA and CTLA-4 antibodies increases the CD8+T/Treg ratio and the CD4+Tconv/Treg ratio, significantly inhibiting tumor growth." (PMID 38500876, 2024). "As previously stated, IT applied to AML comprises checkpoint inhibitors (anti-PD-1, anti-PD-L1, anti-CTLA-4), T cells genetically redirected to leukemia cells (CAR-T therapies), antibodies against tumor antigens (GO, anti-CD33 antibodies), NK cell-based therapies, among others." (PMID 38400148, 2024). "Furthermore, there appears to be a synergistic effect with the combination of radiation and anti-CTLA4, whereby anti-CTLA4 inhibits Tregs and radiation increases the TCR exposure to diverse tumor antigen." (PMID 39199689, 2024). "Tex cells exhibit elevated inhibitory receptors (PD-1, CTLA-4, TIM-3, TIGIT, LAG-3), reduced antitumor cytokines (IFN-γ, IL-2, TNF), increased tumor-promoting chemokines, altered transcription factors (TCF1, T-bet, TOX), metabolic issues, and decreased proliferation and survival." (PMID 39717767, 2024). "Furthermore, we included molecules such as CTLA-4 and LAG-3, which are important for optimal regulation and homeostasis of T cells within the tumor microenvironment." (PMID 38893183, 2024). "Other authors suggest using GITR-specific agonists after developing antigen-specific T cells, which boost T cell response against tumor antigens, with concomitant use of molecules that block negative signaling (e.g., CTLA4, PD-1)." (PMID 39061246, 2024). "The proportion of tumor-infiltrating CD45+ immune cells was elevated in response to the combination group compared to the single-agent treatment groups (anti-CD47 Ab and anti-CTLA4 Ab alone)." (PMID 38398223, 2024). "Additionally, CTLA4 is markedly upregulated by CUL5 knockout, and its inactivation further enhances the anti-tumor effect of CUL5 KO." (PMID 38242867, 2024).
tumor (continued). "Additionally, immune checkpoint molecules (e.g., CCR4, CD27, CD274, CD68, CTLA4, PDCD1, and PDCD1LG2) were significantly upregulated in the AERShigh group (all p < 0.01), suggesting potential impairment of the anti-tumor immune response." (PMID 39464883, 2024). "When anti-CTLA-4 antibody was administered alongside radiation therapy and anti-CD40 mAb therapy, it overcame Treg-mediated immune suppression, resulting in a higher ratio of cytotoxic T cells, tumor rejection, and the development of long-term immunity." (PMID 39629128, 2024). "On combination treatment with anti-CTLA4 (Ipilimumab), besides depletion of Treg and lowering of IL10 release, the spatial dynamics between CTL and Treg affected the incremental efficacy in tumor killing on combination treatment correlated with significant increase in distance between CTL and Treg." (PMID 38383563, 2024). "When assessing tumor-infiltrating exhausted CD8+ T cells with exhaustion unique gene markers, such as Lag3, Tigit, Havcr2, Ctla4, and Pdcd1, we observed that the Lag3 and Tigit levels in the MnBuOE/RT group were significantly lower than those in the other groups (p < 0.05)." (PMID 38671924, 2024). "Furthermore, CTLA-4 inhibitors have been demonstrated to deplete Tregs in the TME and enhance cytotoxic T lymphocyte (CTL)-mediated anti-tumor immunity through enhanced antigen recoginition." (PMID 39068460, 2024). "Y1.7LI-rechallenged mice that rejected Y1.7LI upon neoAg SLP vax or anti-CTLA-4 and/or anti-PD-1 initiated on day 7, but not untreated naive mice, showed no detectable tumor upon secondary challenge." (PMID 39446585, 2024). "In combination with PD-L1 or CTLA-4 targeted therapy, anti-VISTA antibody therapy has shown tumour regression and synergistic effect in preclinical tumour models, suggesting it might help overcome immune check point inhibitor drug resistance." (PMID 39060374, 2024). "We assessed the tumor histology by H&E and immunohistochemistry by staining for the expression of CD3 and CD8; there was a significant increase in CD3+ T cells in Anti‐PD‐1/CTLA‐4 and APG‐157/Anti‐CTLA‐4 groups." (PMID 38686626, 2024). "Additionally, in prostate cancer patients treated with ipilimumab, a high expression of VISTA has been observed, indicating that the combined blockade of CTLA-4 and VISTA presents a promising strategy for enhancing anti-tumor efficacy." (PMID 38500876, 2024). "However, the tumor growth delay was more pronounced when both anti-CD47 Ab and anti-CTLA4 Ab were administered together compared to the single-agent treatment groups." (PMID 38398223, 2024). "These agents work by blocking the interactions of PD-1, CTLA-4, NKG2A, TIGIT, etc. with their ligands on cancer cells, releasing the “brakes” of T and NK cells to eliminate cancer cells more efficiently, promoting long-lasting anti-tumor responses." (PMID 39682686, 2024). "Tumor immune dysfunction and exclusion (TIDE), a computational method that mimics the two major mechanisms of tumor immune evasion, has the ability to predict the prognosis of patients with tumors receiving first-line anti-PD1 or anti-CTLA4 therapy." (PMID 39026679, 2024). "According to our hypothesis, we found that LDHi enhances the activity of CTLA-4 blockade in delaying B16 and MC38 tumor growth, with greater antitumor effects of the combination than each treatment alone." (PMID 39225102, 2024). "Apart from CTLA-4 and PD-1/PD-L1, LAG-3 has emerged as a promising target for tumor immunotherapy." (PMID 38375475, 2024). "Overall, the addition of MDMs to T cell-tumor cell co-cultures induced proinflammatory factors such as TNF secretion, elevated CTLA4 mRNA expression which is known to increase in response to T cell activation and simultaneously decreased anti-inflammatory CCR4 and TGFB1 mRNA expression." (PMID 39414902, 2024).
tumor (continued). "We previously performed spatial proteomic profiling on overlapping samples from the RCC TMAs to characterize expression patterns of multiple tumor immunomarkers, including CD3, PD-1, PD-L1, LAG3, TIM-3, and CTLA-4 in immune cells (CD45+), and PD-L1 in tumor cells (CK+)." (PMID 39105820, 2024). "As anticipated, upon encountering tumor antigens, the tumor-specific CTLs in conjunction with LPS-RGD-Nb36-DOX were able to quickly blockade the CTLA-4/B7 axis, as seen by increased expression of CD25, CD69, and CD62L as well as increased cytokine secretion (TNF-α, IFN-γ, and IL-2)." (PMID 38824143, 2024). "As expected, H2O mice receiving anti-CTLA4 showed significantly reduced tumor growth and significantly prolonged survival compared to H2O mice that did not receive anti-CTLA4." (PMID 38500667, 2024). "Further, analysis of the anti-tumor cytotoxicity (E:T ratio 20:1) of CD8+ and CD4+T cells demonstrated a 3.9- and 6.8-fold increased response (respectively) following combinatorial treatment of anti-CTLA4 mAb with anti-TGFβ mAb, compared to isotype treatment." (PMID 38891044, 2024). "Clinical trials are exploring inhibitors of CTLA-4 and TGF-β for pancreatic cancer, with early-phase studies indicating that combining these inhibitors with immune checkpoint blockade can enhance anti-tumor immune responses and improve outcomes." (PMID 39539544, 2024). "Importantly, CTLA-4 has been found to be overexpressed in certain types of HCC, which can lead to the uncontrolled growth and spread of the tumor via this “downregulating” pathway." (PMID 38893164, 2024). "CTLA-4 can block CD28-B7 interaction and can instead bind to B7 molecules itself with higher affinity, thus leading to impaired T cell effector function and hindering tumor immunity." (PMID 39534873, 2024). "Anti-CTLA-4 Ab treatment resulted in recruitment of interferon-gamma (IFN-g)-producing CD4+ T cells, called T-helper 1 (Th1), into tumors, and neutralization of IFN-g abrogated the anti-tumor effects." (PMID 39106430, 2024). "Also, an anti-CTLA-4 DNA aptamer and a dual function aptamer (anti-CTLA-4/PD-L1) have shown that an anti-CLTA-4 aptamer can promote T lymphocyte proliferation, inhibit tumor growth, and strengthen anti-tumor immunity." (PMID 38473398, 2024). "Ipilimumab, the first FDA-approved monoclonal antibody targeting the negative immune checkpoint protein CTLA-4, enhances T cell activation and depletes Tregs in the tumor bed." (PMID 38711620, 2024). "However, as anticipated, CTLA4 and CUL5 DKO showed a superior anti-tumor ability compared to either CTLA4 KO or CUL5 KO alone." (PMID 38242867, 2024). "Notably, silencing Dusp18 resulted in a deceleration of xenograft tumor growth, accompanied by increased levels of IFN-γ and GzmB expression, and a decrease in the percentage of PD-1+, TIM-3+, and CTLA-4+ CD8+ T cells." (PMID 38992029, 2024). "We found that CDN4 only responded in combined immunotherapy with anti-PD-1/CTLA-4, which may contribute to the dual blockade of PD-1/CTLA-4 increasing effector T-cell activity to enhance tumor suppression." (PMID 38461356, 2024). "B. pseudolongum administration combined with anti-CTLA-4 immunotherapy was found to induce Th1 differentiation and effector T cell function, which was supported by elevated IFN-γ production in splenic CD4+ and CD8+ T lymphocytes in tumor-free mice." (PMID 37046762, 2023). "However, by combining LIGHT-VTP with checkpoint blockade of both CTLA-4 and PD-1 (termed ‘LIGHT-VTP triple therapy’) there was an inhibition of tumour growth, necrotic haemorrhaging and prolonged survival." (PMID 37287625, 2023). "Contrary to our expectations, mild tumor regression was observed in the SiLN contralateral to the anti-CTLA4 injected SiLN but not the anti-CTLA4 injected SiLN." (PMID 37259163, 2023). "At the same time, the PEGylated one showed longer blood half-lives and tumor accumulation compared to non-PEGylated liposomes and free CTLA-4." (PMID 37106400, 2023).